PRDX4 (peroxiredoxin 4)
Diseases named in the same sentence as PRDX4 in open-access papers (continued):
Sharing a sentence is not in itself a finding about the gene and the disease.
liver failure (2 papers, 2018 to 2020). A liver disease characterized by the liver losing or has lost all of its function. "The results revealed that the DKO mice spontaneously develop severe liver failure accompanied by increased levels of oxidative stress and the ER stress occurs early in life, suggesting that Sod1 and Prdx4 have protective roles against liver failure." (PMID 30050648, 2018).
metabolic syndrome (2 papers, 2019 to 2021). A cluster of metabolic risk factors for CARDIOVASCULAR DISEASES and TYPE 2 DIABETES MELLITUS. "PRDX4 has emerged as an important player in numerous diseases, such as fibrosis and metabolic syndromes, and its overoxidation is a potential indicator of ER redox stress." (PMID 33895140, 2021).
myeloma (2 papers, 2013 to 2022). "Because PRDX4 is an important component of the ER folding machinery, we speculated that changes in the amount of iIgL in myeloma cells with altered OTUD1 expression might be caused by variations in the PRDX4 protein quantity." (PMID 36357400, 2022). "Here, the authors show that deubiquitinase OTUD1 protects PRDX4 from degradation resulting in increased load of misfolded immunoglobulins sensitizing myeloma cells for proteasome inhibition." (PMID 36357400, 2022). "On the other hand, differences in myeloma cell proliferation caused by differential OTUD1 expression were not changed by normalizing PRDX4 protein levels or by restoring the IgL levels." (PMID 36357400, 2022). "At the same time, none of the tested phenotypes altered upon OTUD1 expression in myeloma cells (Ig production, proliferation, PI sensitivity) was affected by the absence of the KEAP1-binding site in OTUD1, prompting us to further investigate the role of PRDX4." (PMID 36357400, 2022).
renal carcinoma (2 papers, 2020 to 2024). A carcinoma arising from the epithelium of the renal parenchyma or the renal pelvis. "Other osteoclastogenesis mediators, including peroxiredoxin-4 (PRDX4) and L-plastin (LPC1), have been identified as responsible for tumor bone colonization in a number of osteotropic cancers such as breast, prostate, and renal cancers." (PMID 32582538, 2020).
steatosis (2 papers, 2019 to 2020). Increased lipid within the cytoplasm of cells. "Prdx4 helps prevent steatosis progression, metabolic syndrome, inflammatory reactions and apoptotic activity by suppressing local and systemic oxidative stress." (PMID 33311472, 2020). "Prdx4 is an antioxidant, anti-steatosis, anti-inflammatory and anti-apoptotic substance." (PMID 33311472, 2020).
type 1 diabetes (2 papers, 2014 to 2024). "Mechanistically, PRDX4 promoted the degradation of dipeptidyl peptidase-4, which is associated with DR in type 1 diabetics, thereby alleviating HG-stimulated Müller cell abnormalities." (PMID 39706273, 2024).
acute myeloid leukemia (1 paper, 2011). Acute myeloid leukemia (AML) is a group of neoplasms arising from precursor cells committed to the myeloid cell-line differentiation. "Here, we investigated whether PRDX4 is affected in acute myeloid leukemia (AML); genomic alterations and expression levels of PRDX4 were investigated." (PMID 21283726, 2011).
acute pancreatitis (1 paper, 2024). An acute inflammatory process that leads to necrosis of the pancreatic parenchyma. "We found that the pathological injury score of pancreatic tissue in mice with acute pancreatitis was significantly increased and accompanied by increased Prdx4 expression compared with the control group." (PMID 38641608, 2024). "The findings revealed highly expression of Prdx4 in fibroblasts, endothelial cells, and epithelial cells during acute pancreatitis, as well as in NKT cells, macrophages, granulocytes, and B cells." (PMID 38641608, 2024). "The central gene Prdx4 exhibited significant correlations with the aggregation of various immune cell types in acute pancreatitis." (PMID 38641608, 2024). "In the study of Qingyi Granules ameliorating acute pancreatitis, it was found that Prdx4 may be involved in signaling during the pathological injury of severe acute pancreatitis by analyzing the proteomics of pancreatic tissue." (PMID 38641608, 2024). "The observed positive correlation between Prdx4 and immunoactive cells, specifically activated CD8 T cells and Th17 cells, implies that diminished levels of Prdx4 in the context of acute pancreatitis could potentially facilitate immune tolerance." (PMID 38641608, 2024).
Anxiety (1 paper, 2019). Intense feelings of nervousness, tension, or panic often arise in response to interpersonal stresses. "Given these previous links with anxiety behaviour, PRDX4 is an excellent candidate for tonic immobility behaviour both in the chicken and in other vertebrates." (PMID 31067744, 2019). "PRDX4 is involved in neurogenesis, regulation of HIF1-alpha, and has previous links to anxiety and sociality behaviour." (PMID 31067744, 2019). "We find that tonic immobility shows no phenotypic correlation with inverted restraint behaviour; however, both PRDX4 and ACOT9 are also strong candidates for sociality/anxiety behaviour in the chicken." (PMID 31067744, 2019).
B-cell neoplasm (1 paper, 2025). A group of heterogeneous lymphoid tumors generally expressing one or more B-cell antigens or representing malignant transformations of B-lymphocytes. "Prdx4 expression is induced in B cell neoplasms and associated with the synthesis and secretion of immunoglobulin light chains." (PMID 40165976, 2025).
breast tumors (1 paper, 2023). "Three downregulated markers, PEA15, PRDX4, and FN1, also showed low protein expression in breast tumors, as confirmed with immunohistochemistry staining." (PMID 37128318, 2023). "However, downregulated secretome markers FN1, PSMB6, PRDX4, and PEA15 are also upregulated at the mRNA level in breast tumors." (PMID 37128318, 2023).
cholestasis (1 paper, 2018). Impairment of the bile flow caused by obstruction within the liver, or outside the liver in the bile duct system. "In this study, we examined the in vivo net effects of PRDX4 overexpression in a murine model of cholestasis." (PMID 30149550, 2018). "All of these features suggest that activators of PRDX4 may be a novel treatment for ameliorating the severity of cholestatic liver injury and improving the prognosis of patients with cholestasis." (PMID 30149550, 2018). "Taken together, these findings suggest that PRDX4 may be more effective as a cholestasis therapy than other antioxidants." (PMID 30149550, 2018). "Taken together, we thus can hypothesize that PRDX4 might be able to play an important role in the pathophysiologic processes of cholestatic liver injury and to influence the progression and prognosis of cholestasis." (PMID 30149550, 2018). "Therefore, in the present study, PRDX4 may have attenuated cholestasis-induced liver injury by reducing extracellular oxidant stress and mitochondrial dysfunction, thereby suppressing the release of inflammatory cytokines and neutrophil infiltration." (PMID 30149550, 2018). "Interestingly, the composition of the hepatic bile acids (BAs) was more beneficial for Tg BDL mice than for WT BDL mice, suggesting that PRDX4 overexpression may affect BA metabolism during cholestasis." (PMID 30149550, 2018). "Extracellular PRDX4 may play a larger role in protecting against cholestasis-induced liver injury." (PMID 30149550, 2018).
chronic myeloid leukemia (1 paper, 2024). "Moreover, GSEA results showed that B cell receptor signaling pathway, chronic myeloid leukemia, FC-gamma-R- mediated phagocytosis, pathogenic Escherichia collineation and spliceosome were mainly enriched in AP samples or low expression Prdx4 group." (PMID 38641608, 2024).
endometrial cancer (1 paper, 2024). Primary or metastatic malignant neoplasm involving the endometrium (mucous membrane that lines the endometrial cavity). "ERS-induced ER peroxidase PRDX4 and the important molecular chaperone GRP78 are highly expressed in endometrial cancer tissues, indicating synergistic relations; their co-expression is an independent risk factor for endometrial cancer prognosis and overall survival." (PMID 38711526, 2024).
fibrosis (1 paper, 2019). the formation of excess fibrous connective tissue in an organ or tissue in a reparative or reactive process. "However, increased serum PRDX4 level was associated with an aggravation of pulmonary inflammatory changes, fibrosis, and poor prognosis in the murine model; therefore, elevated serum PRDX4 levels observed in patients with AE-IPF may originate from increased PRDX4 expression in the lungs." (PMID 31888585, 2019). "In addition, we examined the pathogenetic roles of PRDX4 in pulmonary inflammation and fibrosis using Tg mice in a BLM-induced PF model." (PMID 31888585, 2019).
Fungal infection (1 paper, 2017). "Fungal infection also increased the mRNA expression and protein production of heme oxygenase-1 (HMOX1) and cyclooxygenase-2 (COX2), with suppressed levels of antioxidant enzymes, superoxide dismutase-1 (SOD1), glutathione peroxidase-1 (GPx1) and peroxiredoxin-4 (PRDX4)." (PMID 28874754, 2017).
heart failure (1 paper, 2022). Inability of the heart to pump blood at an adequate rate to meet tissue metabolic requirements. "A recent report posits downregulation of SR-specific Peroxiredoxin-4 (PRDX4) increases oxidative stress in cardiac fibroblasts and contributes to heart failure." (PMID 36425292, 2022).
hepatic disorders (1 paper, 2018). "Using DKO mice in which both Sod1 and Prdx4 were deleted, we show that oxidative stress in association with ER stress leads to the development of a very severe hepatic disorder." (PMID 30050648, 2018).
hepatoblastoma (1 paper, 2020). Hepatoblastoma (HB) is a malignant hepatic tumor and is the most common pediatric liver cancer. "The latest study in hepatoblastoma (HB) indicated that PRDX4 promoted embryonal hepatoblastoma cell migration but induced fetal hepatoblastoma cell differentiation." (PMID 33456675, 2020).
interstitial lung disease (1 paper, 2019). A diverse group of lung diseases that affect the lung parenchyma. "In addition, an increase in the PRDX4 mRNA expression in the lung tissue of patients with interstitial lung disease was reported, but the role of PRDX4 in the pathogenesis and progression of IPF is still unclear." (PMID 31888585, 2019).
kidney cancer (1 paper, 2021). Primary or metastatic malignant neoplasm involving the kidney. "Increased or decreased levels of PRDXs mRNA expression levels were found among 33 tumor types, such as PRDX1, PRDX2, PRDX4 and PRDX5 increased in several cancer types, while PRDX3 and PRDX6 decreased in there types of kidney cancer (KIRP, KIRC and KICH)." (PMID 34246267, 2021). "Notably, when compared to adjacent or normal tissues, PRDX1, PRDX2, PRDX4 and PRDX5 were significantly up-regulated expression in several cancer types (UCEC, READ, BLCA, BRCA, CHOL, COAD, LIHC, THCA), while PRDX3 and PRDX6 were down-regulated expression in kidney cancers." (PMID 34246267, 2021).
liver cancer (1 paper, 2015). An epithelial or non-epithelial malignant neoplasm that arises from the liver. "GTT might directly influence the expression dynamics of peroxiredoxin-4 to control proliferation in liver cancer." (PMID 25886747, 2015).
lung adenoma (1 paper, 2020). A benign, well circumscribed epithelial neoplasm that arises from the bronchus or the lung parenchyma. "In accordance with the elevated MMP9 expression, the expression of CD31 was observed to be increased in PRDX4 Tg tumor tissue, indicating a higher density of microvessels which benefits the development of lung adenoma in mice." (PMID 33456675, 2020). "In the present study, we examined the effect of PRDX4 overexpression on the development of lung adenoma induced by urethane by comparing tumor formation between PRDX4 transgenic (Tg) mice and non-Tg mice." (PMID 33456675, 2020). "In the present study, we demonstrated the overexpression of PRDX4, the only secreted member of the PRDX family, promoting tumor development in urethane-induced lung adenoma." (PMID 33456675, 2020).
lymphoma (1 paper, 2016). A malignant (clonal) proliferation of B- lymphocytes or T- lymphocytes which involves the lymph nodes, bone marrow and/or extranodal sites. "Interestingly, downregulation of TRX inhibitory protein VDUP1, and upregulation of PRDX3 and PRDX4, correlated with poor prognosis of DLBCL patients, indicating tumor-promoting role of TRX-like enzymes in lymphomas." (PMID 26636537, 2016).
metastasis (1 paper, 2022). The spread or migration of cancer cells from one part of the body (where they first appeared) to another. "We found that Gelsolin and PRDX4 are linked together, whose levels are influenced as a prognostic and predictive biomarker in CRC tumor tissues with lymph node metastasis (LNM) stage IV." (PMID 35804959, 2022).
myeloid leukemia (1 paper, 2011). A clonal proliferation of myeloid cells and their precursors in the bone marrow, peripheral blood, and spleen. "Next, we analyzed PRDX4 expression levels in 461 myeloid leukemia patients measured on gene expression arrays." (PMID 21283726, 2011).
neuroblastoma (1 paper, 2015). Neuroblastoma (NB) is the most common solid, extracranial childhood tumor. "LDHA and PRDX4 were described as overexpressed in high-risk neuroblastomas independently of other markers." (PMID 25869207, 2015).
osteosarcoma (1 paper, 2017). A usually aggressive malignant bone-forming mesenchymal neoplasm, predominantly affecting adolescents and young adults. "The authors found that 8 proteins, including HSP70, UQCRC1, and PRDX4, were increased in osteosarcoma and therefore may be potential molecular targets for osteosarcoma diagnosis and therapy." (PMID 28387323, 2017).
Parkinson disease (1 paper, 2017). A progressive degenerative disorder of the central nervous system characterized by loss of dopamine producing neurons in the substantia nigra and the presence of Lewy bodies in the substantia nigra and locus coeruleus. "Five to seven pQTL were observed for phosphoglycerate mutase 1 (PGAM1), the putative Parkinson disease autosomal recessive early onset 7 variant 1 (PARK7), triose phosphate isomerase (TPI1), peroxiredoxin 4 (PRDX4), malate dehydrogenase 1 (MDH1) and 3-hydroxyanthranilate 3,4-dioxygenase (HAAO)." (PMID 28424047, 2017).
peripheral artery disease (1 paper, 2021). "Prdx4 has recently been identified in the circulation of both healthy individuals and patients with peripheral artery disease (PAD)." (PMID 34439492, 2021).
renal cell carcinoma (1 paper, 2025). "This study demonstrates that resveratrol inhibits the activation of the Wnt/β‐catenin signaling pathway by downregulating PRDX4 expression, thereby suppressing renal cell carcinoma (RCC) progression." (PMID 40458080, 2025).
renal fibrosis (1 paper, 2016). A final common manifestation of a wide variety of chronic kidney diseases characterized by glomerulosclerosis and tubulointerstitial fibrosis. "To determine involvement of Prdxs in renal fibrosis, we analyzed the expression pattern of Prdxs isotypes (Prdx1, Prdx2, Prdx3, Prdx4, Prdx5, and Prdx6) in the cortex/outer stripe of outer medulla of UUO kidney." (PMID 26872211, 2016).
Shock (1 paper, 2024). The state in which profound and widespread reduction of effective tissue perfusion leads first to reversible, and then if prolonged, to irreversible cellular injury. "Studies have demonstrated that Prdx4 co-localizes with inflammasome components in extracellular vesicles from inflammasome-activated macrophages, and is a critical regulator of inflammasome activity, which can reduce the susceptibility of mice to LPS-induced septic shock." (PMID 38641608, 2024).
silicosis (1 paper, 2025). Silicosis is a respiratory disease caused by breathing in (inhaling) silica dust. "In vivo studies in a silicosis mouse model demonstrated that pharmacological inhibition of PRDX4 using conoidin A (Con A) significantly improved lung function, reduced fibrosis and inflammatory infiltration, and decreased collagen deposition and lung damage." (PMID 41373732, 2025).
tendinopathy (1 paper, 2023). "PRDX4 and GPX7 were upregulated in tendinopathy samples; however, because their expression levels were quite low, the effect of this upregulation was not assumed to be significant." (PMID 37021050, 2023).